PFKFB4 (6-phosphofructo-2-kinase/fructose-2,6-biphosphatase 4)
Diseases named in the same sentence as PFKFB4 in open-access papers (continued):
Sharing a sentence is not in itself a finding about the gene and the disease.
myeloma (1 paper, 2022). "Treatments with the PFKFB3 inhibitor, PFK158, and PFKFB4 inhibitor, 5MPN, were found to inhibit the growth of myeloma cells." (PMID 35578370, 2022). "Our data also suggest that administration of PFKFB3 and PFKFB4 inhibitors may be a powerful strategy against myeloma cells and to enhance the cytotoxic effects of proteasome inhibitors in hypoxic conditions." (PMID 35578370, 2022).
osteoarthritis (1 paper, 2025). A noninflammatory degenerative joint disease occurring chiefly in older persons, characterized by degeneration of the articular cartilage, hypertrophy of bone at the margins and changes in the synovial membrane. "Given that chondrocytes in osteoarthritis often exhibit decreased proliferation and migration, we conducted in vitro experiments to evaluate the effects of PFKFB4 and DDIT4on ATDC5 cells proliferation and migration." (PMID 39846237, 2025). "The RT‐qPCR further confirmed that PFKFB4 and DDIT4 expression at the mRNA level was lower in osteoarthritis cartilage tissue than in normal cartilage tissues." (PMID 39846237, 2025).
prostatic small cell neuroendocrine carcinomas (1 paper, 2017). "Most of prostatic small cell neuroendocrine carcinomas were strongly positive for PFKFB4, in contrast, the adenocarcinoma cells were negative or weakly stained." (PMID 29029419, 2017).
renal cell carcinoma (1 paper, 2021). "Similarly, we confirmed the interaction between NCOA3 and PFKFB4 to modulate PPP flux in renal cell carcinoma." (PMID 34593007, 2021).
sarcoidosis (1 paper, 2020). Sarcoidosis is a multisystemic disorder of unknown cause characterized by the formation of immune granulomas in involved organs. "Additional pathways that were different between progressive and non-progressive sarcoidosis in the BALF included CD28 signaling and PFKFB4 signaling." (PMID 32764642, 2020).
Skin Cutaneous Melanoma (1 paper, 2022). "Further, the relative mRNA expression of PFKFB4 in SKCM (Skin Cutaneous Melanoma) data from TCGA (The Cancer Genome Atlas) combined with Skin data from GTEx (Genotype-Tissue Expression) was significantly higher (p < 2.22e-16) in tumor (469 samples) than that of normal (557 samples)." (PMID 36034839, 2022).
small cell neuroendocrine carcinoma (1 paper, 2020). "The findings from another study showed that the expression of PFKFB4 was significantly higher in small cell neuroendocrine carcinoma than in adenocarcinoma, which suggested that increasingly aggressive PCa might be related to increasingly high PFKFB4 expression." (PMID 32487245, 2020).
squamous cell carcinoma (1 paper, 2022). A carcinoma arising from squamous epithelial cells. "In an evaluation of patient tumor samples of different cancer entities, PFKFB4 protein was found to be overexpressed in prostate, lung, colon, mammary and squamous cell carcinoma, with expression level correlating with tumor grade." (PMID 36115843, 2022). "In TMA staining, the level of PFKFB4 protein expression in colon, mammary and squamous cell carcinoma ranges from not expressed (score 0) to highly expressed (score 2), with normal tissue being mostly negative for PFKFB4." (PMID 36115843, 2022).
cancer (75 papers, 2013 to 2025). A tumor composed of atypical neoplastic, often pleomorphic cells that invade other tissues. "Recently, it has been reported that PFKFB4 is associated with cancer proliferation, metastasis and progression in multiple tumour cell types." (PMID 36127291, 2023). "Our data show that a kinase-deficient form of PFKFB4 still retains important cancer-promoting functions outside of glycolysis regulation." (PMID 35914811, 2022). "PFKFB4 has also been implicated in the metastatic process during cancer progression." (PMID 39595571, 2024). "Moreover, we found that PFKFB4 is associated with drug resistance and cancer stemness in OSCC cells." (PMID 37919747, 2023). "We also investigated their biological roles in OSCC cells, which PFKFB3 is linked to critical aspects such as cell survival, G2/M cell cycle progression, invasion, and migration, while PFKFB4 is strongly associated with drug resistance and the acquisition of cancer stemness characteristics." (PMID 37919747, 2023). "Furthermore, the most frequently altered PC1 genes, PFKFB4, had substantial copy-number loss via shallow deletions across glycolytic cancers." (PMID 36831501, 2023). "PFKFB4, in particular, plays a crucial role in glucose metabolism within cancer cells by facilitating the reversible conversion of fructose-2,6-bisphosphate to fructose-6-phosphate, a key step in the glycolysis pathway." (PMID 40739397, 2025). "Accumulating evidence suggests that PFKFB4 plays a crucial role in glycolytic metabolism, cancer stemness, and hypoxic adaptation, providing potential mechanistic insights into lenvatinib resistance." (PMID 40269756, 2025). "PFKFB4 is vital in glucose metabolism in cancer cells, converting fructose-2,6-bisphosphate to fructose-6-phosphate, a crucial step in glycolysis." (PMID 40739397, 2025). "It is possible that DNMT3B regulates the expression of PFKFB4 by methylating its promoter region, thereby modulating glycolytic activity in cancer cells." (PMID 39595571, 2024). "Our data showed that PFKFB3 and PFKFB4 play different roles; PFKFB3 is involved in cell viability, G2/M cell cycle progression, invasion, and migration, whereas PFKFB4 is involved in the drug resistance and cancer stemness of OSCC cells." (PMID 37919747, 2023). "Apart from glycolysis, PFKFB4 governs cancer progression through various mechanisms-regulating transcription through phosphorylating SRCs, affecting autophagy or inducing the production of hyaluran, a major constituent of ECM." (PMID 37222403, 2023). "Our analyzed data confirmed the possible effect of PFKFB3 in cell cycle progression and migration as well as the effect of PFKFB4 in cancer stemness in OSCC." (PMID 37919747, 2023). "PFKFB4 has a more active kinase activity than phosphatase, and it is also overexpressed in several human cancers." (PMID 36914921, 2023). "Two isozymes of PFK2, i.e. PFKFB3 and PFKFB4, showed elevated expression in many cancer types and are involved in altered glycolysis." (PMID 37222403, 2023). "PFKFB3 and PFKFB4 are the most overexpressed and active isoforms in a plethora of cancers; these two isoforms are responsible for the common upregulation of F-2,6-BP seen in cancer cells." (PMID 38201444, 2023). "A pan-cancer analysis of PFKFB4 expression using the TIMER2.0 database demonstrated increased PFKFB4 mRNA levels in multiple malignancies, including COAD." (PMID 37770581, 2023).
cancer (continued). "We further explored the effects of PFKFB3 and PFKFB4 on chemoresistance and cancer stemness in OSCC cells." (PMID 37919747, 2023). "The resultant PFKFB4 promotes cancer cell stemness properties via up-regulation of aerobic glycolysis in cancer cells." (PMID 37894408, 2023). "Studies have shown that PFKFB4 controls the formation of reactive oxygen species (ROS) by directing glucose metabolic intermediates to the PPP in various cancer cells." (PMID 37770581, 2023). "Increased expression of PFKFB4 regulates fructose-2,6-bisphosphate and responds to hypoxia to help cancer cells produce more ATP." (PMID 37834191, 2023). "This undermines current strategies to counteract PFKFB4 in cancer, which involves developing pharmacological drugs to interfere with PFKFB4 kinase activity, assuming that PFKFB4’s major function in cancer is to promote glycolysis and Warburg effect." (PMID 35914811, 2022). "Knocking down the expression of PFKFB4 makes reactive oxygen species easy to accumulate in cancer cells and further induces autophagy." (PMID 36109523, 2022). "First, we used the Tumor Immune Estimation Resource (TIMER2.0) database to explore the expression of PFKFB4 in several cancers." (PMID 35902861, 2022). "PFKFB4 thus displays a novel function, important to modulate the activity of a major cell signaling pathway in cancer cells." (PMID 35914811, 2022). "This newly discovered function of PFKFB4, coupled with its cancer specificity, provides a new strategy for inhibiting HIF-1α in cancer cells." (PMID 36115843, 2022). "To address the relevance of PFKFB4 in a broader cancer context, we investigated the expression of PFKFB4 protein in patient samples of a range of cancer entities." (PMID 36115843, 2022). "The obtained results evidence that RIPOR2 and PFKFB4 are deregulated in CC patients and in C33-E616 and C33-E7 CC cell lines, suggesting that their modulation in this cancer type is partially mediated by E6 and E7 oncoproteins." (PMID 36497200, 2022). "We here extend the parallel between the two models, showing increased expression of PFKFB4 in development and cancer as predicted by our previous WGCNA analyses." (PMID 35914811, 2022). "We thus provide evidence of a novel and glycolysis-independent function of PFKFB4 in human cancer cells." (PMID 35914811, 2022). "In this study, we further evaluated the role of PFKFB4 in the survival of cancer cells, particularly focusing on GSCs." (PMID 36115843, 2022). "Hif1α activates transcription of Pfkfb4, which leads to enhanced glycolysis and increased ATP production in cancer cells." (PMID 35917405, 2022). "In cancer, the intriguing relationships between PFKFB4, cell signaling and cell migration remain unexplored." (PMID 35914811, 2022). "In conclusion, our study pointed a need for proper analysis of PFKFB4 isoforms to understand the complex process of metabolic changes in cancer." (PMID 34445551, 2021). "Of note, many of the regulatory steps of PFKFB4 have been reported separately in individual cancers." (PMID 34593007, 2021). "PFKFB4 was also differentially expressed in ccRCC with contrasting difference of expression between normal and cancer samples amongst all cancers." (PMID 34593007, 2021). "Overall, these studies strongly indicate a role of PFKFB3 and PFKFB4 in the invasiveness of cancer cells." (PMID 33671514, 2021). "In actual fact, the carcinogenic role of PFKFB4 has been documented in a variety of malignant tumors, including in HCC." (PMID 34970545, 2021). "In accord with above cancers, we found that PFKFB4 was overexpressed in renal tumor cells which suggested worse prognosis, and it functioned as a regulator in metabolic programming to induce proliferation, migration and invasion of RCC." (PMID 34593007, 2021). "PFKFB3 and PFKFB4 stimulate glucose uptake and boost glycolytic flux to cancer cells by increasing F-2,6-BP, which is a compound promoting glucose utilization by glycolysis." (PMID 33671514, 2021).
cancer (continued). "It is highly possible that PFKFB4 act as the failsafe to counteract excessive hypoxia-induced ROS incurred either by selective pressure or anti-cancer agents like Sunitinib." (PMID 34593007, 2021). "There is also evidence showing that the FBPase-2 domain of PFKFB4 is important for cancer cell survival, which indicates the phosphatase domain as a new potential therapeutical target for cancer." (PMID 35056904, 2021). "Because of the key role of CDK6 in PFKFB4-overexpressing tumors, palbociclib administration is considered an effective strategy for this type of cancer." (PMID 34211613, 2021). "In hormone-sensitive stage, ADT inhibited proliferation and glycolytic activity of cancer cells which potentially inhibited PFKFB4 as well." (PMID 32487245, 2020). "In this regard, intriguing possibilities include PFKFB3 and PFKFB4 (6-phosphofructo-2-kinase/fructose-2,6-biphosphatases 3 and 4), which play important roles in regulating glycolytic flux, especially in cancer cells." (PMID 30651087, 2019). "Our results, together with previous mechanistic studies, provide a rationale for further clinical investigation to treat cancer by manipulating PFKFB4 expression." (PMID 31244553, 2019). "Initially, using the R2 data base we analyzed the relation between PFKFB3 and PFKFB4 expression and the overall survival rate in the panel of cancers." (PMID 31754349, 2019). "In fact, studies in recent years revealed that PFKFB3/PFKFB4 isoenzymes are excellent candidates for glycolysis targeting, especially in cancer cells." (PMID 31754349, 2019). "PFKFB4 plays an important role in regulating glucose metabolism and directing metabolic pathways required for biosynthesis of macromolecules to maintain cancer cell proliferation." (PMID 31244553, 2019). "Nevertheless, up to this day, most research on PFK-II refers to one of the two cancer specific isoenzymes PFKFB3 or PFKFB4, undoubtedly neglecting the importance of co-expression of individual isoenzymes." (PMID 31754349, 2019). "Recent studies suggest that metabolic isoenzymes of phosphofructokinase II (PFK-II) – PFKFB3 and PFKFB4, often induced in hypoxic environment, significantly contribute to enhancement of glucose metabolism and in consequence cancer progression." (PMID 31754349, 2019). "Several groups independently identified PFKFB4 as a key metabolic enzyme in cancer using high-content screening." (PMID 31244553, 2019). "Several in vitro studies revealed that targeting PFKFB3 and PFKFB4 in cancer cells results in glycolysis inhibition and in consequence, attenuation of tumor growth." (PMID 31754349, 2019). "In this sense, targeting of both PFKFB3 and PFKFB4 isoenzymes has been proposed to be advantageous due to their high expression in some cancer cells." (PMID 30234009, 2018). "Apart from the importance of PFKFB4 in regulating cancer cell glycolysis, its expression also determines the metabolic adaptation of non-tumor cells." (PMID 30234009, 2018). "By contrast, PFKFB4 that is expressed in other types of transformed cells and tumors synthesizes Fru-2,6-P2 and is required for the glycolytic reprogramming of cancer cells." (PMID 30234009, 2018). "The main function of PFKFB4 in cancer cells has been an area of debate, with a number of studies indicating a predominant phosphatase activity and others suggesting a dominant kinase activity." (PMID 28152500, 2017). "PFKFB4 has been shown to be expressed in multiple organs and to be overexpressed in human tumours, indicating a potential role in cancer development and/or progression." (PMID 27769068, 2016). "Malignant tumor growth is supported also by altered activity of several glycolytic enzymes such as the overexpression of hexokinase and 6-phosphofructo-2-kinase/fructose-2,6- bisphosphatase-4 (PFKFB-4) that enhanced the flux through glycolysis." (PMID 27029038, 2016). "Until now, few studies have demonstrated that PFKFB4 is induced by hypoxia and required for the survival and growth of several cancer cell lines." (PMID 27769068, 2016).
cancer (continued). "Taken together, these studies show that, in the majority of cancer cells, the kinase domain of PFKFB4 dominates to synthesize F2,6BP driving glycolytic flux into the 3-carbon portion of the pathway and enabling both ATP and anabolic substrate production." (PMID 26221874, 2015). "Vice versa, the depletion of 6-phosphofructo-2-kinase/fructose 2,6-bisphosphatase 4 (PFKFB4) inhibits cancer cell growth by lowering flux through the PPP." (PMID 25243985, 2015). "Researchers have also linked biological markers of glycolysis (HK2, PFKFB4, PKM2, etc.)with tumor recurrence and OS in certain cancer patients." (PMID 26576639, 2015). "In this study, we report the discovery of a first-in-class and highly specific small molecule antagonist of the kinase domain of PFKFB4 that suppresses glucose metabolism and the proliferation of multiple cancer types." (PMID 26221874, 2015). "PFKFB4 is over-expressed in human cancers, induced by hypoxia and required for survival and growth of several cancer cell lines." (PMID 25115398, 2014). "To summarize, these data indicate that the kinase activity and, thus, the capacity to produce F2,6BP, serves as the dominant function of PFKFB4 in cancer cells." (PMID 25115398, 2014). "PFKFB4 shows predominantly bisphosphatase activity, leading to the suggestion that these cancer cells rely on PFKFB4 to dampen glycolytic flux, promote the PPP and manage ROS accumulation - very similar to the proposed action of TIGAR." (PMID 24383451, 2014). "Last, we find that PFKFB4 is required for cancer cell survival during the metabolic response to hypoxia, presumably to enable glycolytic production of ATP when the electron transport chain is not fully operational." (PMID 25115398, 2014). "Accordingly, the synthesis of small molecule inhibitors of the PFKFB4 kinase domain is anticipated to enable the development of novel agents for the treatment of cancer." (PMID 25115398, 2014). "Interestingly, central carbon metabolism in cancer (HK2, MAPK3, MYC, PFKP, PKM2, SLC16A3), galactose metabolism (B4GALT2, HK2, PFKP) and fructose and mannose metabolism (HK2, PFKFB4, PFKP) are associated with metabolism." (PMID 39924557, 2025). "Numerous studies have reported the overexpression of PFKFB4 in various human cancers." (PMID 40213972, 2025). "PFKFB4 up-regulates TKT expression by driving SRC-3 activation and glucose flow to the PPP, thereby providing conditions for rapid division and proliferation, and causing proliferation and metastasis of cancer cells." (PMID 38434975, 2024). "Epigenetic regulation and metabolic pathways are known to be interconnected, and there is evidence to suggest that DNMT3B and PFKFB4 may interact in a manner that contributes to the development and progression of cancer." (PMID 39595571, 2024). "Considering that PFKFB4 is a key bifunctional enzyme in glycolysis, we speculated that palbociclib promotes cancer stemness via PFKFB4‐mediated glycolysis." (PMID 36127291, 2023). "On the other hand, we revealed that PFKFB4 involves in chemoresistance and cancer stemness of OSCC." (PMID 37919747, 2023). "Taken together, our results indicate that PFKFB4 might be involved in the chemoresistance and cancer stemness of OSCC." (PMID 37919747, 2023). "The expression of PFKFB2, PFKFB3, and PFKFB4 has been observed in several types of cancers." (PMID 37919747, 2023). "Furthermore, PFKFB3 is involved in the growth and metastasis of OSCC cells, but PFKFB4 is involved in chemoresistance and the cancer stemness of OSCC cells." (PMID 37919747, 2023). "In addition, previous studies have shown that PFKFB4 is activated in hypoxia and overexpressed in various types of tumour tissues, especially in metastatic and recurrent malignant tumours." (PMID 36127291, 2023).